CASP1 (caspase 1)
Diseases named in the same sentence as CASP1 in open-access papers (continued):
Sharing a sentence is not in itself a finding about the gene and the disease.
colitis (continued). "Cleaved-caspase-1 in colitis mice colon was markedly decreased by evodiamine, so was the ratio of cleaved caspase one to pro-caspase 1, it suggested that caspase-1 activation in vivo was inhibited by evodiamine." (PMID 33240089, 2020). "IL-1β protein levels were increased in IL-10 KO mice, but a caspase-1 inhibitor significantly improved spontaneous colitis in these mice." (PMID 33143375, 2020). "DSS treatment significantly induced increases in the protein levels of NLRP3, ASC, IL-1β, and caspase-1 in the colons of the colitis mice." (PMID 33312339, 2020). "In these studies, it was observed that the greatest susceptibility to the development of colitis in ASC-/-, NLRP6-/-, NLRP1-/-, NLRP3-/-, AIM2-/- or caspase-1-/- mice was related to a decrease in IL-18 levels." (PMID 32545788, 2020). "At 20 day after Cg treatment, high-resolution live colonoscopy analyses revealed that Nlrp3−/−, Pycard−/− and Casp1/11−/− were protected from Cg-induced colitis." (PMID 32894139, 2020). "Mice deficient in NLRP3, Casp1/11, ASC, and IL-1β have all demonstrated an increased susceptibility to DSS-induced colitis, disease exacerbation and more frequent mortality when compared to WT mice." (PMID 30873162, 2019). "Asc−/− mice develop markedly more severe pathology after dextran sodium sulfate (DSS)-induced colitis than wild-type (WT) and Casp1−/− mice." (PMID 31379813, 2019). "Our understanding for the roles of ASC and Caspase-1 during DSS-induced colitis are currently being re-defined." (PMID 30214011, 2018). "Treatment with IL-1 receptor antagonist or caspase-1 inhibitors suppressed IL-1β and IL-17 production, thus ameliorating spontaneous colitis in IL-10−/− mice." (PMID 28179906, 2017). "Herein, we found that celastrol significantly ameliorated colitis carrying the suppression of cleaved caspase-1 and IL-1β secretion." (PMID 28978034, 2017). "Colorectal instillation of DCA in mice strongly aggravates DSS-induced colitis and caspase-1 inhibition as well as macrophage depletion substantially alleviates colonic inflammation and injury." (PMID 27965665, 2016). "Intriguingly, A438079 treatment significantly diminished active caspase-1 expression in colitis mice." (PMID 26739809, 2016). "During the progression of colitis, active caspase-1 expression was dramatically induced in lamina propria immune cells." (PMID 26739809, 2016). "Initial studies show that pharmacological inhibition of caspase-1 with Pralnacasan or neutralization of IL-18 confers resistance to experimental colitis." (PMID 24886810, 2014). "The authors found that mice deficient for NLRP3 inflammasome components including NLRP3, ASC or caspase-1 had severe colitis and increased tumorigenesis in AOM/DSS colon cancer model." (PMID 25120559, 2014). "Recent studies examining the molecular mechanisms by which NLRP3 and caspase-1 control integrity of the intestinal epithelium during experimental colitis point to a critical role of NLRP3 in gut mucosal immune homeostasis." (PMID 25071778, 2014). "For example, dextran sodium sulfate-mediated colitis and MSU-induced joint inflammation in a murine model of gout are less severe in mice deficient in caspase-1 or NLRP3." (PMID 23977231, 2013). "Caspase-1, as well as Nlrc6 and Asc, limit mucosal injury in dextran sodium sulfate induced colitis through the modulation of the intestinal microbiota." (PMID 23977202, 2013). "Since generation of active IL-18 requires caspase-1, studies have also been performed in mice deficient in caspase-1 and subjected to DSS colitis." (PMID 24115947, 2013). "Additionally, the colitis rat model validated the upregulation of Irf1 and Casp1 at both mRNA and protein levels." (PMID 40018047, 2025). "Furthermore, IL-18 has been shown to be essential for mucosal homeostasis: mice deficient in Nlrp3, Pycard/Asc, caspase-1, IL-18, or IL-18R—all components of the inflammasome pathway—are highly susceptible to DSS-induced colitis." (PMID 40869366, 2025).
colitis (continued). "Furthermore, both the mRNA and protein expression of Irf1 and Casp1 were significantly upregulated in the colitis rats compared to the controls." (PMID 40018047, 2025). "Moreover, mice deficient in inflammasome components such as NLRP3, caspase-1, or ASC have an enhanced susceptibility to DSS-colitis." (PMID 37681916, 2023). "Interestingly, in this publication it was shown that intraperitoneal injection of DCA worsened DSS-induced colitis and this effect was abrogated by addition of caspase-1 inhibitor or macrophage depletion." (PMID 38090554, 2023). "Caspase-1-deficient or NLRC4-deficient mice show increased colonic epithelial cell proliferation and reduced tumor cell apoptosis resulting in enhanced tumor formation in the colitis-associated colorectal cancer models." (PMID 36932407, 2023). "They showed that it could reduce MDA, NO, MPO, hydroxyproline, TNF-α, IL-1β, IL-6, iNOs mRNA, COX-2 mRNA, IFN-γ mRNA, Bcl-2-associated X protein (Bax), Caspase-1, NF-kB and IκBα and increase IL-10, SOD and GSH in an in vivo model of TNBS-induced colitis." (PMID 36677021, 2023). "Numerous experimental studies on animals have demonstrated inhibiting Caspase-1-dependent pyroptosis could protect against DSS-induced colitis." (PMID 37954856, 2023). "Importantly, the pyroptotic cells were remarkably weakened, as evidenced by decreasing the percentage of TUNEL-positive cells and abolishing the fluorescence intensity of caspase-1 in colon tissues under the administration of SM934 in colitis mice." (PMID 36120344, 2022). "We investigated whether SM934 exerted a protective effect against TNBS-induced colitis via the blockade of the canonical inflammasome caspase-1-mediated pyroptosis activation." (PMID 36120344, 2022). "Furthermore, CHR down-regulates LPS-elicited TNF-α, IL-6, and COX-2 expressions by suppressing the activation of NF-κB and Caspase-1, helping resist colitis." (PMID 35599576, 2022). "Interestingly, different studies investigating the role of the NLRP3/CASP1 pathway in mice with DSS-induced colitis are either in line with our findings or report the complete opposite." (PMID 35911682, 2022). "Although the role of the NLRP3 inflammasome in murine IBD models with NLRP3, ASC, or caspase-1 deficiency remains controversial, inhibitors targeting the NLRP3 inflammasome, such as MCC950, oridonin, and INF39, have anti-inflammatory effects in colitis models." (PMID 35330829, 2022). "In conclusion, our study demonstrated that oral administration of SM934 exerted therapeutic effects in experimental colitis induced by TNBS via inhibiting the IECs’ apoptosis and blocking the caspase-1-mediated pyroptosis-associated NLRP3/NF-κB/MAPK signal pathways." (PMID 36120344, 2022). "CPT-11 could activate inflammasome NLRP3, promote caspase-1 to cleaved the precursor of IL-1β and release a large amount of mature IL-1β into colonic tissue, resulting in colitis." (PMID 34025639, 2021). "Therefore, the use of chemical inhibitors of caspase-1, IL-1β and IL-18 can help to understand the exact role of these molecules in colitis pathogenesis." (PMID 34571825, 2021). "AMPK inhibitor (Dorsomorphin, 10 mg/kg) not only suppressed p-AMPK and Nrf2 protein expression levels, but also induced NLRP3 and Caspase-1 protein expression levels in DSS-induced colitis mice treated with Schisandrin B, in comparison to the group treated with Schisandrin B." (PMID 34628369, 2021). "The presence of cleaved caspase-1 together with biosensor activation in the brains of mice treated with DSS is a strong indicator that an inflammasome(s) is active in this tissue during colitis." (PMID 34758843, 2021). "In early reports, caspase-1 is often involved in the exacerbation of colitis." (PMID 33143375, 2020).
colitis (continued). "In caspase-1-deficient mice, tumorigenesis was increased in the Azoxymethane–Dextran sodium sulfate (AOM–DSS)-induced, colitis-associated colon cancer model, and the colonic epithelial cell proliferation in the early stage of tumorigenesis, and tumor cell proliferation was found." (PMID 31941010, 2020). "Andrographolide (Compound 10), the bitter diterpene lactone, at 7.5 and 15 mg/kg exerted an anti-colitis and anti-tumor effect by lowering the expression of cleaved CASP1, IL-1β, and mitochondrial membrane potential collapse via the PIK3CA–AKT1–MTOR–RPS6KB1 pathway." (PMID 33101293, 2020). "Conversely, loss of Nlrp3 or Caspase-1 expression in CD4+ T cells did not confer a highly colitogenic phenotype in vivo in a T-cell adoptive transfer colitis model." (PMID 31379813, 2019). "Based on this background, the present study was designed to investigate how the direct blockade of NLRP3 with INF39 in experimental colitis compares, in terms of efficacy, with other drugs acting downstream (caspase-1 inhibition or IL-1β receptor blockade) on NLRP3 signaling." (PMID 30559669, 2018). "Results from these studies show that mice deficient for inflammasome components, including NLRP3, caspase-1, NLRP1, NLRP6, and NLRC4, are highly susceptible to colitis-associated colon cancer induced by AOM/DSS by displaying severe intestinal inflammation, and increased number of colon polyps." (PMID 28955343, 2017). "In particular, treatment with wogonoside, a glucuronide metabolite of the bioactive flavonoid wogonin, reduced significantly colonic NF-κB and NLRP3 expression, as well as caspase-1 expression and activity in mice with colitis, exerting beneficial effects on colonic inflammation." (PMID 28179906, 2017). "In addition, we observed a positive correlation of the percentage of NLRP3 and cleaved caspase-1 double-stained cells with the severity of colitis (Matts’ grading score) in patients with UC." (PMID 27966619, 2016). "Furthermore, pharmacological inhibition of IL-1β or Caspase-1 was shown to successfully ameliorate intestinal inflammation in colitis animal models." (PMID 27965665, 2016). "Moreover, treatment with inhibitor of P2 × 7 receptor, A438079, decreased NFκB activation and active caspase-1 expression in lamina propria immune cells, downregulated proinflammatory cytokine production in colon tissues, and attenuated murine colitis." (PMID 26739809, 2016). "Similar phenotypes have been observed in caspase-1–deficient mice, and also in mice deficient in the canonical inflammasome components, NLRP3 and ASC, suggesting that the noncanonical inflammasome is activated in vivo during acute DSS-colitis." (PMID 25548224, 2015). "Furthermore, administration of exogenous IL-18 can alleviate the severity of colitis and colitis-induced tumorigenesis in caspase-1/11 and Nlrp3 KO mice." (PMID 23847622, 2013). "In addition, treatment of mice with a specific caspase-1 inhibitor was also effective in protecting against the colitis." (PMID 24115947, 2013). "Several potential therapeutic targets have emerged, including caspase-1 inhibitors, the preclinical studies have shown that inhibiting caspase-1 can reduce the severity of colitis in animal models, suggesting that pharmacological modulation of this enzyme may provide therapeutic benefits." (PMID 40271055, 2025). "While these findings may help to explain why specific blockade of caspase-1 had previously been reported to ameliorate inflammatory symptoms in murine spontaneous colitis models, the exact functions of specific NLR inflammasomes in IBD remains incompletely resolved." (PMID 31231388, 2019). "In this study, we have noted that DSS-induced colitis is characterized by drastic increment of active caspase-1 expression in lamina propria immune cells, whereas blockade of P2 × 7 receptor by its pharmacological inhibitor dampens active caspase-1 levels in lamina propria of colitis." (PMID 26739809, 2016).
colitis (continued). "Nevertheless, despite many studies, the role of caspase-1 in DSS colitis remains unclear." (PMID 24115947, 2013). "For instance, the experimental colitis induced by DSS or 2,4,6-trinitrobenzenesulfonic acid was significantly alleviated by either knocking out NLRP3 and caspase-1 genes or administering pyroptosis inhibitors." (PMID 40041420, 2025). "Colitis induction significantly elevated macroscopic damage scores, stool consistency, inflammatory cytokines, MDA, MPO, and NLRP3, NF-κB, caspase-1, while reducing GSH levels (p < 0.001-0.01)." (PMID 40320895, 2025). "Increased levels of cleaved caspase-1 protein in macrophages from CD patients and in TNBS-induced colitis mice further support the involvement of caspase-1 in CD pathogenesis." (PMID 40018047, 2025). "When treated with dextran sulfate sodium (DSS), mice with knockout of caspase-1 and NLRP3 showed considerable improvement in colitis." (PMID 40041420, 2025). "NLRP3 mediates the conversion of pro-caspase-1 to its mature form to generate IL-1β and IL-18, while caspase-1-mediated inflammasome pathways control TNBS-induced colitis in mice." (PMID 40244120, 2025). "Immunoblotting analysis showed substantially increased caspase-1 p20 and GSDMD-NT in colonic tissues from colitis mice relative to water control mice." (PMID 39113799, 2024). "RT-qPCR analysis results showed that EIF treatment significantly reduced the expression of inflammasome component genes (NLRP3, caspase-1, and ASC) and IL-1β in the colon tissue of DSS-induced colitis mice." (PMID 39408295, 2024). "The changes in the expression of inflammasome component genes (NLRP3, caspase-1, ASC) and IL-1β in the colon tissue of DSS-induced colitis mice following EIF treatment were examined using RT-qPCR." (PMID 39408295, 2024). "A series of research showed that mice deficient in NLRP3 signaling components, including NLRP3, ASC and CASP1, were more likely to develop DSS-induced colitis." (PMID 37833958, 2023). "In the present study, we demonstrated an important activation of the NLRP3 complex following DNBS-induced colitis; however, Ulva pertusa treatments significantly decreased NLRP3, ASC, and Caspase-1 expressions, lessening NLRP3 inflammasome activity." (PMID 37233492, 2023). "Using caspase-1/11-/-, NLRP3-/-, NLRC4-/-, IL18-/-, and IL22-/- mice, we showed that KLPJ-mediated colitis occurred through activation of caspase-11, and was dependent on IL18 and partly on IL22." (PMID 36436756, 2023). "In mouse colitis model, MCC950 was demonstrated to act on NLRP3 by inhibiting ASC oligomerization and caspase-1 dependent activation of IL-1β and IL-18, and reducing the levels of pro-inflammatory cytokines." (PMID 37681916, 2023). "Mice treated with SCH experienced significant weight gain, effectively alleviating the severity of colitis, and decreasing the levels of inflammatory factors such as TNF-α, IL-1β, IL-18, IL-6, and other related proteins (NLRP3, Caspase-1, SGK1) in UC mice." (PMID 37674245, 2023). "Pharmacological blockade, through small molecule inhibitors or Gly-Pro-Ala (GPA) peptide isolated from fish skin gelatin hydrolysate, of the Caspase-1-GSDMD pathway attenuated pyroptotic events, improving colitis." (PMID 37891577, 2023). "VAD mice demonstrated severe experimental colitis and increased expression of inflammasome-related proteins (caspase-11, GSDMD, NLRP3, ASC, caspase-1, IL-1β, and IL-18) in the colonic LP." (PMID 37240022, 2023). "DSS is not only a well-studied induction model for colitis, but DSS can also induce caspase-1 cleavage via activation of the NLRP3 inflammasome." (PMID 35246034, 2022). "Previousfindings indicate that NLRP3, ASC, and caspase-1 expression aresignificantly upregulated in colitis; inhibition of the NLRP3 inflammasomepathway effectively reduces the severity of colitis." (PMID 39076616, 2022).
colitis (continued). "This molecule has demonstrated an inhibitory effect against the NLRP3 signaling pathway, decreasing the protein levels of NLRP3, ASC, caspase-1 p45, and caspase-1 p20 in the colon tissue of BALB/c mice with induced colitis." (PMID 35276849, 2022). "The mRNA expressions of NLRP3, ASC, caspase-1, GSDMD, IL-18, and HMGB1 were shown to increase in different extents in colitis tissues than in control tissues, whereas SM934 treatment decreased the expression of these genes." (PMID 36120344, 2022). "In a DSS-induced mouse colitis model, the use of VX765 (a caspase-1 inhibitor), which inhibits caspase-1/GSDMD pathway-regulated pyroptosis, attenuates colitis in mice." (PMID 35677444, 2022). "The suppression of colitis by MSPNPs was further investigated by assessing the expression levels of NLRP3 inflammasome and caspase-1." (PMID 35745756, 2022). "Mice treated with MCC950, a specific NLRP3 inhibitor, experienced resolution of acute or chronic colitis by inhibiting ASC oligomerization, caspase-1 dependent activation of IL-1β and IL-18, and reducing pro-inflammatory cytokines." (PMID 36199683, 2022). "Roseburia intestinalis, a butyrate−producing bacterium, -derived flagellin was demonstrated to inhibit the activation of NLRP3/caspase-1/GSDMD signaling-triggered pyroptosis in macrophages by targeting miR−223−3p and ameliorate colitis." (PMID 36505474, 2022). "In this study, the expression of NLRP3, ASC, and Cleaved caspase-1 was increased while the expression of CLDN1, OCLN, and ZO-1 was decreased in colon tissues of colitis mice, which were reversed by YST to near normal levels." (PMID 34055024, 2021). "SCFA acetate binding to metabolite‐sensing receptors GPR43 and/or GPCR109A has been shown to mediate a protective effect against colitis and drive activation of NLRP3 inflammasome in epithelial cells, showing caspase 1 activation and secretion of IL‐18." (PMID 33682108, 2021). "The major components and effector molecules of the inflammasome, such as NLRP3, ASC, AIM2, Caspase 1, Caspase 11, IL-18, and IL-1β, play important roles in DSS-induced colitis." (PMID 34721422, 2021). "Protein levels of mature IL-1β and cleaved caspase-1 were increased in colon tissues of Slco2a1-knockout mice treated with DSS, which led us to hypothesize that NLRP3 inflammasome activation might contribute to the exacerbation of DSS colitis in Slco2a1-deficient mice." (PMID 32184453, 2020). "For instance, two recent studies showed that both the in vivo caspase-1 inhibition and the selective blockade of NLRP3 inflammasome complex significantly attenuated colonic inflammation in spontaneous colitis mice." (PMID 30559669, 2018). "Compared with the vehicle group, treatment with HU 308 (1 mg/kg, i.p.)significantly decreased NLRP3, the Casp-1 p20/Casp-1 p45 ratio and proIL-1β in colon from DSS-induced colitis mice." (PMID 27611972, 2016). "Colitis was induced by OXA treatment in NLRP3−/− mice and caspase-1−/− mice to determine the involvement of NLRP3 and caspase-1 in this disease process." (PMID 27966619, 2016). "On one hand, absence of NLRP3 inflammasomes and caspase-1 has been shown to increase the inclination of mice towards developing colitis in response to DSS, even leading to mortality." (PMID 40041420, 2025). "Mice without ASC, caspase-1, or NLRP3 had more severe colitis and tumorigenesis in colitis-associated cancer models." (PMID 40141358, 2025). "Recent studies elucidate the potent protective effects of Ruscogenin against DSS-induced colitis, demonstrating its ability to alleviate the condition in mice by inhibiting the activation of the NLRP3 inflammasome and the caspase-1-dependent canonical pyroptosis." (PMID 40271055, 2025). "In addition, punicalagin has been shown to exert anti-inflammatory and microbiota-modulating effects in murine colitis models, as well as attenuating ventricular remodeling after acute myocardial infarction through regulation of the NLRP3/caspase-1 pathway." (PMID 40362057, 2025).